TRIM47 (tripartite motif containing 47)
Diseases named in the same sentence as TRIM47 in open-access papers (continued):
Sharing a sentence is not in itself a finding about the gene and the disease.
tumor (continued). "Furthermore, silencing TRIM47 resulted in a decrease in CD68+CD206+ cells within the tumor tissues, whereas overexpression of TRIM47 led to an increase in CD68+CD206+ cells in the same tissues." (PMID 41380966, 2025). "As for the actions of TRIM47 in cancer pathogenesis and progression, a study recommends that TRIM47 joins in the modulation of ubiquitination-mediated degradation of oncogene products or tumor suppressors." (PMID 40618019, 2025). "Given that dysregulated cell proliferation in malignancies frequently correlates with cell cycle aberrations and apoptotic resistance, and considering the established role of TRIM47 in modulating these processes across various tumor types, we sought to investigate its specific functions in LC." (PMID 41460629, 2025). "For example, in more aggressive undifferentiated TC, GSK-3β activity is higher, which may further promote the phosphorylation of ADAR and TRIM47-mediated degradation, thereby exacerbating tumor progression." (PMID 40618019, 2025). "In terms of fumarate level, TRIM47 silence reduced the fumarate level in tumor tissues." (PMID 41380966, 2025). "Moreover, the xenograft tumours in the TRIM47 downregulation groups were much lighter than those in the control groups." (PMID 40801794, 2025). "Notably, we focused on TRIM47, the only differentially expressed member of the TRIM family linked to poor prognosis in ICC, which was significantly elevated in the tumor tissues of ICC patients." (PMID 41380966, 2025). "Notably, TRIM47 depletion dramatically suppressed HepG2-derived tumor formation, demonstrating its critical role in LC growth in vivo." (PMID 41460629, 2025). "Similarly, inhibition of PLK1 in vivo effectively attenuated TRIM47-mediated tumor promotion in xenograft models." (PMID 41460629, 2025). "Furthermore, the TUNEL staining results indicated that the number of apoptotic cells was reduced in tumor tissues overexpressing TRIM47." (PMID 41460629, 2025). "Conversely, the opposite effect was observed in tumor tissues where TRIM47 was overexpressed." (PMID 41380966, 2025). "Furthermore, stable TRIM47 knocking-down Huh7 cells and overexpressing Hep3B cells (and related control cells) were used to generate subcutaneous xenograft modes to verify the effect of TRIM47 on tumor growth." (PMID 41460629, 2025). "For example, in the clinical sample analysis, patient-related variables such as age, gender, tumor stage, and previous treatment regimens could influence the expression of TRIM47 and other biomarkers." (PMID 40618019, 2025). "Importantly, pharmacological inhibition of PLK1 effectively abrogated TRIM47-driven tumor growth in xenograft models." (PMID 41460629, 2025). "Notably, TRIM47 mRNA levels positively correlated with advanced tumor stage and lymph node metastasis." (PMID 41460629, 2025). "Furthermore, overexpression of TRIM47 accelerates many tumor progressions by regulation of aerobic glycolysis, Wnt/β-catenin pathway, PI3K/Akt pathway, and degradation of SMAD4." (PMID 36906594, 2023). "In agreement with the in vitro results, in vivo subcutaneous tumor model experiments showed that TRIM47 overexpressing cells formed smaller tumors compared with vector-transformed cells in Olaparib treatment group, but there was no significant change in the vehicle group." (PMID 36906594, 2023). "Finally, the authors generated a xenograft tumor model by intravenous injection of TRIM47 knockdown SKOV3 cells into nude mice to further assess the influence of TRIM47 on tumor growth in vivo." (PMID 36288633, 2022). "Silencing of STAT3 partially prevented TRIM47–induced tumor cell proliferation and invasion." (PMID 36288633, 2022). "Moreover, the tumor growth was significantly slower in mice injected with TRIM47 knockout cells and the weight of the tumor showed significantly difference between the KO-TRIM47-769P group and WT-769P group (P < 0.01)." (PMID 33622324, 2021).
tumor (continued). "TRIM47 mRNA was significantly overexpressed in tumor tissues compared to normal adjacent tissues." (PMID 28186994, 2017). "Mechanistic investigations demonstrated that TRIM47 remodels energy metabolism by glycolytic reprogramming through its interaction with the K51 site of fructose-1,6-bisphosphatase (FBP1) through K48-linked ubiquitination, thereby promoting HCC proliferation and tumor metastasis." (PMID 41632101, 2026). "Therefore, these tumor metabolic–related proteins may regulate ICC cell metabolic reprogramming through direct or indirect interactions with TRIM47, which is worthy of in-depth investigation in future work." (PMID 41380966, 2025). "In breast cancer, TRIM47 has been shown to activate the NF-κB signaling pathway by promoting the polyubiquitination of PKC-ε, which enhances the malignant phenotype of the tumor." (PMID 41380966, 2025). "On the basis of the proven tumor-promoting effect of TRIM47, a PLK1 plasmid was transfected into TRIM47-knockdown LC cell lines to counteract the retardation of proliferation caused by TRIM47 interference." (PMID 41460629, 2025). "TRIM47 interacted with ADAR to facilitate ADAR protein degradation via ubiquitination, which resulted in the exacerbation of TC tumor expansion, invasion, and metastasis." (PMID 40618019, 2025). "Coexpression of TRIM47 and ICC marker CK19 was observed in patient samples, with both of them exhibiting elevated expression in tumor tissue samples, indicating the occurrence of ICC." (PMID 41380966, 2025). "As we approved, through binding with GSK-3β protein, TRIM47 can enhance ADAR protein stability and ubiquitination so that TRIM47 endorses ADAR-mediated promotion of tumor migration and survival capability." (PMID 40618019, 2025). "In conclusion, the present study shows that TRIM47 positively regulates STAT3 signaling, thereby promoting tumor growth and progression." (PMID 36288633, 2022). "Next, we found that downregulation of TRIM47 remarkably reduced CRC tumor growth and tumor weight in xenograft mouse tumor model." (PMID 30979374, 2019). "TRIM47 exerts an inhibitory effect on SMAD4 by ubiquitylating and degrading SMAD4, thereby promoting tumor growth and progression." (PMID 30979374, 2019). "However, in the tumor microenvironment (TME), TRIM47 undergoes profound functional reprogramming driven by specific post-translational modifications (PTMs) and altered substrate availability." (PMID 42292357, 2026). "TRIM47 was identified as a negative regulator of FH expression in ICC cells and tumor tissues." (PMID 41380966, 2025). "Because OC is primarily a tumor of epithelial origin, the expression of TRIM proteins was analyzed in epithelial cells, and the eight most highly expressed genes (TRIM28, TRIM27, TRIM33, TRIM38, TRIM47, TRIM56, TRIM8, and TRIM24) were determined." (PMID 38881325, 2024). "The expression of TRIM27 and TRIM47 was remarkably higher in KIRC tumor compared to that in normal tissues, and their increased expression was associated with worse OS, indicating an oncogenic role in KIRC." (PMID 35371994, 2022). "In addition, the number of Ki-67-positive tumor cells was lower, whereas the number of TUNEL-positive cells was higher in the TRIM47 knockdown group than in the controls." (PMID 36288633, 2022). "Meanwhile, TRIM47 can activate the NFκB-EMT pathway, thus promoting tumor metastasis." (PMID 28186994, 2017). "Since we had demonstrated that TRIM47 promoted LC proliferation by stabilizing PLK1 through ubiquitination in vitro, we then intended to explore whether the regulatory mechanism was the same in the tumor xenograft model." (PMID 41460629, 2025).
tumor (continued). "The expression of TRIM47 in samples from patients with ICC was examined, revealing that TRIM47 levels were higher in tumor tissues compared with nontumor tissues." (PMID 41380966, 2025).
cancer (18 papers, 2017 to 2026). A tumor composed of atypical neoplastic, often pleomorphic cells that invade other tissues. "While tripartite motif-containing 47 (TRIM47), a typical E3 ubiquitin ligase, has been implicated in cancer progression, its precise role in LC pathogenesis remains unclear." (PMID 41460629, 2025). "In cancer research, TRIM47 has been found to be upregulated in some cancers, such as ovarian cancer, glioma angiogenesis and breast cancer." (PMID 41460629, 2025). "Collectively, these data demonstrate that TRIM47 is responsible for cancer cell proliferation, migration, and invasion in vitro and thus represents a potential therapeutic target for OS patients." (PMID 40801794, 2025). "What cannot be ignored is TRIM47 has been extensively studied in cancer as an E3 ubiquitin ligase that enhances the ubiquitination and degradation of substrate proteins." (PMID 41380966, 2025). "Previous studies have shown that TRIM47 has a variety of complex functions in cancer, including as an E3 ubiquitin ligase." (PMID 41460629, 2025). "GEPIA database showed that the expression of TRIM47 in the cancer tissues was much higher than that in adjacent tissues." (PMID 40618019, 2025). "In the relationship with cancers, TRIM47 was shown to be responsible for ubiquitination and degradation of SMAD4, which led to chemoresistance in response to 5-fluorouracil (5-FU) therapy in colorectal cancer." (PMID 35954308, 2022). "We also discuss the functions of Efp and TRIM47 in other types of cancers and innate immunity by introducing substrates the are modified by poly-ubiquitination." (PMID 35954308, 2022). "The migration and invasion ability of NSCLC cells were assessed to investigate the function of TRIM47 in the metastasis of cancer cells." (PMID 28186994, 2017). "Notably, the secretion of fumarate was reduced in TRIM47-silenced cancer cells, and the treatment of dimethyl fumarate, a derivative of fumarate, reversed the effect of TRIM47 downregulation on M2 polarization in macrophages." (PMID 41380966, 2025). "In mammals, Trim47 functions as a multifunctional regulator, driving tumor progression through ubiquitin-dependent proteolysis and oncogenic signaling while participating in inflammatory and immune pathways, positioning it as a therapeutic target in cancer." (PMID 40709172, 2025). "TRIM47 has been reported to be highly expressed in various cancers and to play a procancer role." (PMID 41380966, 2025). "Cancer cells with TRIM47 downregulation were sensitive to macrophage cytotoxicity." (PMID 41380966, 2025). "Although previous studies reported that TRIM47 was overexpression in several cancers, but, the mechanism of TRIM47 upregulation in cancer remains unknown." (PMID 36906594, 2023). "Tripartite Motif 47 (TRIM47) protein plays a prominent role in many cancers." (PMID 36288633, 2022). "TRIM47 is localized at 17q25.1, a region that is frequently amplified in numerous other cancers." (PMID 36288633, 2022). "Therefore, we believe that TRIM47 is an important proto-oncogene involved in the development and progression of various malignant tumors." (PMID 33622324, 2021).
infection (3 papers, 2017 to 2025). The state of being infected such as from the introduction of a foreign agent such as serum, vaccine, antigenic substance or organism. "TRIM47-shRNA infection caused a significant increase of G0/G1 phase cells and a decrease of S and G2/M phase cells compared with the NC group." (PMID 28186994, 2017). "To directly test if an increase in NS1/2 processing contributes to the resistance of MNV strains to TRIM47, we added the pan-caspase inhibitor z-VAD during infection of control or TRIM47-overexpressing cells." (PMID 41251344, 2025). "The results showed that the mRNA level of TRIM47 increased upon infection with CVS-11 and HEP-Flury strains." (PMID 38731834, 2024). "Unfortunately, we were unable to perform the degradation and ubiquitination experiments during infection, as MNVCR6 viral protein levels are undetectable in TRIM47-expressing cells." (PMID 41251344, 2025). "In the future, determining whether NS1/2 is ubiquitinated during infection will enhance our understanding of MNV biology and the mechanism by which TRIM47 inhibits viral replication." (PMID 41251344, 2025). "Taken together, these data point to a complicated, noncanonical mechanism by which TRIM47 specifically restricts MNVCR6 but not MNVCW3 infection." (PMID 41251344, 2025). "Similarly, while nonstructural proteins were produced in both control and TRIM47-expressing cells infected with MNVCW3, MNVCR6 infection had undetectable levels of viral nonstructural proteins in TRIM47-expressing cells." (PMID 41251344, 2025).
inflammation (1 paper, 2022). Aberrant reaction of the microcirculation characterized by movement of fluid and leukocytes from the blood into extravascular tissues. "In this study, we observed that TRIM47 deficiency significantly alleviated LPS-induced pulmonary inflammation and tissue damage in mice." (PMID 35513381, 2022).
TRIM47 also shares sentences with these, for which no sentence is quoted: glioblastoma (2 papers); acute lung injury (1); colon cancer (1); differentiated thyroid carcinoma (1); esophageal carcinoma (1); intrahepatic cholangiocarcinoma (1); lung adenocarcinoma (1); lung injury (1); prostate adenocarcinoma (1); squamous cell carcinoma (1).